RNF181 (ring finger protein 181)
Description:
E3 ubiquitin-protein ligase which accepts ubiquitin from an E2 ubiquitin-conjugating enzyme in the form of a thioester and then directly transfers the ubiquitin to targeted substrates. Catalyzes monoubiquitination of 26S proteasome subunit PSMC2/RPT1.
Synonyms: HSPC238
Tractability: PROTAC: UniProt records ubiquitination sites on it; ubiquitination databases record sites on it; its protein half-life has been measured.
Gene: Protein-coding gene on chromosome 2 (85,595,693 to 85,598,589, forward strand). Ensembl gene ENSG00000168894.
Subcellular location (Human Protein Atlas): Nucleoplasm; Cytosol
Pathways (Reactome):
Metabolism of proteins: E3 ubiquitin ligases ubiquitinate target proteins
Gene Ontology:
Molecular function: protein binding; ubiquitin protein ligase activity; ubiquitin-protein transferase activity
Biological process: protein autoubiquitination; protein ubiquitination
Cellular component: cytoplasm
Genetic constraint (gnomAD): Loss-of-function variants: 25 observed, 23.87 expected, observed/expected ratio (o/e) 1.05, 90% interval 0.76 to 1.46. The upper end of that interval is the gene's LOEUF score, 1.46, which puts it in group 6 of 6, group 1 being the genes least tolerant of losing a copy. Missense variants: 167 observed, 200.85 expected, observed/expected ratio (o/e) 0.83, 90% interval 0.73 to 0.94. Synonymous variants: 62 observed, 75.32 expected, observed/expected ratio (o/e) 0.82, 90% interval 0.67 to 1.02.
Homologues: Orthologues: chimpanzee RNF181 (99% identical), macaque RNF181 (99% identical), dog RNF181 (93% identical), pig RNF181 (93% identical), rat Rnf181 (88% identical), guinea pig RNF181 (88% identical), tropical clawed frog rnf181 (66% identical), zebrafish rnf181 (65% identical), Drosophila melanogaster CG7694 (38% identical), Caenorhabditis elegans rnf-126 (27% identical). Paralogues in human: RNF126 (33% identical), RNF115 (32% identical).
Diseases named in the same sentence as RNF181 in open-access papers:
RNF181 is named in the same sentence as 17 diseases in open-access papers, as found by Europe PMC text mining. Sharing a sentence is not in itself a finding about the gene and the disease. The quoted sentences say what the papers report.
breast carcinoma (7 papers, 2020 to 2024). "For example, RNF181 promotes breast cancer progression by enhancing K63-linked ubiquitination and stabilization of ERα." (PMID 37524698, 2023). "Our study reports that the E3 ubiquitin ligase RNF181 interacts with and stabilizes ERα protein, possibly through K63-linked ubiquitination, which subsequently facilitates ERα signaling and breast cancer cell progression." (PMID 32973333, 2020). "Since RNF181 could associate with ERα in breast cancer cells, we further investigate the biological effect of such interaction." (PMID 32973333, 2020). "Interestingly, RNF181 could associate with ERα protein level in human breast cancer samples and correlates with poor survival in endocrine therapy patients." (PMID 32973333, 2020). "Our previous research demonstrated that SMURF1, TRIM56 and RNF181 can interact with ERα and enhance breast cancer growth." (PMID 39215346, 2024). "Here, our data implicate that RNF181 is increased in human breast cancer and relates to poor outcome in endocrine therapy patients." (PMID 32973333, 2020). "In our current study, we identifies that the ubiquitin ligase RNF181 stabilizes ERα and facilitates breast cancer progression." (PMID 32973333, 2020). "Three independent clinical cohorts show that RNF181 correlates with poor survival in breast cancer patients with endocrine therapy." (PMID 32973333, 2020). "In our current study, we implicate RNF181 (RING Finger Protein 181) in modulating ERα protein stability and breast cancer progression." (PMID 32973333, 2020). "RNF181 depletion inhibits breast cancer progression in vivo and in vitro, reduces ERα protein level and its target gene expression, such as PS2 and GREB1." (PMID 32973333, 2020). "In order to approach the function of RNF181 in breast cancer cells in an unbiased way, we deplete RNF181 in MCF-7 cells for the whole genomic expression analysis." (PMID 32973333, 2020). "In order to investigate the correlation between RNF181 expression and breast cancer molecular biomarkers, 120 breast cancer tissues are collected for immunohistochemistry (IHC) analysis." (PMID 32973333, 2020). "RNF181 associates with AF1 domain of ERα via its RING domain and prolongs ERα stability, which subsequently enhances ERα target gene expression and breast cancer cell proliferation." (PMID 32973333, 2020). "WST assay shows that RNF181 depletion significantly decreases breast cancer cell proliferation in MCF-7 and T47D cells." (PMID 32973333, 2020). "In order to investigate the impact of RNF181 on breast cancer phenotypes, we deplete RNF181 in breast cancer cells." (PMID 32973333, 2020). "In conclusion, we identified an interesting E3 ligase RNF181 in facilitating ERα signaling in breast cancer cells." (PMID 32973333, 2020). "The survival data analysis shows that RNF181 is correlated with shorter progression-free survival in all breast cancer patients." (PMID 32973333, 2020). "For example, our previous studies showed that RNF181 and SMURF1 could associate with ERα and promote breast cancer proliferation." (PMID 38017133, 2024). "In breast cancer, RNF181 prolongs the stability of ERa associated with AF1 via its RING domain binding to the domain of ERa, and enhancement of the gene expression of ERa promotes breast cancer progression." (PMID 35222523, 2021). "Based on these data, we can propose that the selective modulators or inhibitors, which control RNF181 activity or expression could a promising strategy for ERα positive breast cancer therapeutics." (PMID 32973333, 2020). "In conclusion, our data implicate a non-genomic mechanism by RNF181 via stabilizing ERα protein controls ERα target gene expression linked to breast cancer progression." (PMID 32973333, 2020). "As a novel modulator of Hippo signaling, disturbing RNF181 activity or affecting RNF181 expression could be a plausible way to overcome YAP-driven breast cancer among TNBC patients." (PMID 32655323, 2020).
breast carcinoma (continued). "We analyze the public available data of RNF181 in breast cancer database." (PMID 32655323, 2020). "Besides, public available data showed that RNF181 is elevated in breast cancer and related to poor prognosis in TNBC patients." (PMID 32655323, 2020). "Besides, RNF181 is elevated in breast cancer, compared with normal breast tissue, while both RNF181 and YAP are correlated with poor prognosis in TNBC." (PMID 32655323, 2020). "We further investigate the localization of RNF181 and ERα in breast cancer cells." (PMID 32973333, 2020). "As a novel modulator of ERα signaling, disturbing RNF181 activity or affecting RNF181 expression could be a plausible way to treat luminal types of breast cancer." (PMID 32973333, 2020). "RNF181 could promote breast cancer cell invasion and proliferation via stabilizing ERα protein." (PMID 32973333, 2020). "RNF181 could promote breast cancer progression in vivo and in vitro and facilitate ERα signaling." (PMID 32973333, 2020). "Besides, we also showed that RNF181 was increased in breast cancer." (PMID 32655323, 2020). "This RNF181/circRNA-SFMBT2/ERα ternary complex reduced ubiquitination-mediated ERα degradation and activated ERα signaling to facilitate cell growth and tamoxifen resistance in breast cancer." (PMID 37524698, 2023). "In the subtype analysis, RNF181 correlates with poor survival in Luminal A type and Luminal B type breast cancer, but not with HER2 type and triple negative breast cancer types." (PMID 32973333, 2020). "Our study proves that RNF181 stabilizes ERα protein via a non-proteolytic ubiquitination manner, which provide a novel insight of the RING family protein in ERα signaling and breast cancer progression." (PMID 32973333, 2020).
triple-negative breast carcinoma (5 papers, 2020 to 2026). An invasive breast carcinoma which is negative for expression of estrogen receptor (ER), progesterone receptor (PR), and human epidermal growth factor receptor 2 (HER2). "For instance, RNF181 can modulate signaling pathways that involve Hippo/YAP, CARD11 and ERK/MAPK-cyclin D1/CDK4, and it has been implicated in diseases like triple negative breast cancer and gastric cancer." (PMID 41494040, 2026). "In the uncurable triple-negative breast cancer (TNBC), RNF181 inhibits the K48-linked poly-ubiquitination of YAP, thus promoting YAP stability." (PMID 35222523, 2021). "RNF181 could be an interesting marker for triple negative breast cancer prognostics and therapeutics." (PMID 32655323, 2020).
lymphoma (4 papers, 2019 to 2021). A malignant (clonal) proliferation of B- lymphocytes or T- lymphocytes which involves the lymph nodes, bone marrow and/or extranodal sites. "In a recent study, it was shown that RNF181 functions as an E3 ubiquitin ligase and inhibits antigen receptor signaling to NF-κB, downstream of CARD11, and can influence the signaling output of oncogenic CARD11 variants and the growth of CARD11-dependent human lymphoma cells." (PMID 30530863, 2019). "The interaction between RNF181 and CARD11 may enhance the NF-kB signaling pathway in lymphoma." (PMID 35222523, 2021). "RNF181 could interact with CARD11 and promote NFKB signaling in lymphoma cells." (PMID 32655323, 2020). "RNF181 could interact with CARD11 and promote NKFB pathway in lymphoma." (PMID 32973333, 2020).
colon carcinoma (3 papers, 2020 to 2021). "Besides, RNF181 also facilitates cell viability and angiogenesis in colon carcinoma." (PMID 35222523, 2021). "Besides, RNF181 was shown to promote colon cancer viability and angiogenesis." (PMID 32655323, 2020). "Besides, RNF181 is also proved to facilitate colon cancer survival and angiogenesis." (PMID 32973333, 2020).
breast tumors (1 paper, 2020). "The expression of RNF181 is correlated with ERα level in human breast tumors and relates to poor survival in endocrine-treated patients." (PMID 32973333, 2020).
cardiotoxicity (1 paper, 2021). Toxicity that impairs or damages the heart. "For instance, the gene expression levels of RNF181 and DKK3 were significantly decreased in both DOX- and ISO-induced cardiotoxicity models." (PMID 35222523, 2021).
Coronary Artery Disease (1 paper, 2021). "Furthermore, by GWAS meta-analysis, two risk variants located at the RNF181 locus were identified as associated with coronary heart disease." (PMID 35222523, 2021). "Taken together, RNF181 may serve as a causal gene of prognostic or therapeutic value targeting coronary heart disease." (PMID 35222523, 2021).
viral infection (1 paper, 2026). "To elucidate how the target gene RNF181 affected viral infection, we designed specific double-stranded RNA (dsRNA) to knockdown the expression of RNF181 in BmN cells." (PMID 41494040, 2026).
cancer (4 papers, 2020 to 2026). A tumor composed of atypical neoplastic, often pleomorphic cells that invade other tissues. "Current research indicates that RNF181 can regulate multiple signal transduction pathways and impact various types of cancer in humans." (PMID 41494040, 2026). "Concordantly, Spearman correlation analysis using the data from the TCGA and GTEx projects revealed that RNF181 expression had a significant positive correlation with circRNA-SFMBT2 signaling in most cancer types, particularly in the TCGA pancancer dataset." (PMID 37524698, 2023). "In our current study, we investigate the role of RNF181 in modulating TNBC cancer cell progression." (PMID 32655323, 2020). "In cancers, RNF181 was found to be elevated in several human malignancies." (PMID 32655323, 2020). "RNF181 could stabilize YAP protein and inhibit K48 linked poly-ubiquitination, which leads to enhanced YAP target gene expression and cancer progression in TNBC." (PMID 32655323, 2020). "However, little is known about RNF181 function in human cancer." (PMID 32655323, 2020). "Interestingly, RNF181 is elevated in quite a few human cancers." (PMID 32973333, 2020). "In our current study, we uncover a novel regulatory mechanism between RNF181 and ERα, which provides both novel knowledge of RNF family members in ERα function and a promising strategy for ERα positive cancer therapeutics." (PMID 32973333, 2020).
tumor (4 papers, 2016 to 2023). "Furthermore, the circRNA-SFMBT2/RNF181 axis differentially regulated K48-linked and K63-linked ubiquitination of ERα to enhance ERα stability, resulting in increased expression of ERα target genes and tumor progression." (PMID 37524698, 2023). "As discussed in previous studies, the UPS molecule RNF181 played an important role in tumor biology." (PMID 35222523, 2021). "Our data show that RNF181 depletion inhibits the tumor growth speed in vivo." (PMID 32973333, 2020).
infection (2 papers, 2014 to 2026). The state of being infected such as from the introduction of a foreign agent such as serum, vaccine, antigenic substance or organism. "However, overexpression of RNF181 or treatment with piR-bmo-796514 inhibitor in BmN cells prevented the induction of Integrin α2b-like expression by BmNPV infection at 12 and 24 hpi." (PMID 41494040, 2026). "RNF181 acts as a negative regulator of BmNPV infection since it targets the membrane receptor Integrin α2b-like for ubiquitination and proteasomal degradation, which prevents its interaction with the BmNPV envelope fusion protein GP64 that promotes BmNPV entry." (PMID 41494040, 2026). "Furthermore, analysis of the expression profile of the target gene RNF181 by qPCR showed a significant downregulation of RNF181 in both the fat body (24 hpi) and BmN cells (24 and 48 hpi) following BmNPV infection." (PMID 41494040, 2026). "Moreover, knockdown of RNF181 in BmN cells and subsequent infection with BmNPV revealed a significant increase in virus vp39 expression (24 hpi) and viral DNA load (48 hpi)." (PMID 41494040, 2026). "In the silkworm-BmNPV infection system, it was found that piR-bmo-796514, a host-derived piRNA, could be significantly induced in larval fat body and BmN cells and could target and inhibit the expression of E3 ubiquitin ligase RNF181." (PMID 41494040, 2026). "Here, we demonstrated that infection by Bombyx mori nucleopolyhedrovirus (BmNPV), a large DNA virus, induced significant upregulation of silkworm host piR-bmo-796514, which facilitated viral proliferation by suppressing the expression of E3 ubiquitin ligase RNF181." (PMID 41494040, 2026).
cardiovascular diseases (1 paper, 2021). "Further efforts are required to verify the potent interactions and the regulatory mechanism of RNF181 in CAD and other cardiovascular diseases." (PMID 35222523, 2021).
RNF181 also shares sentences with these, for which no sentence is quoted: cardiac diseases (1 paper); gastric cancer (1); heart failure (1); Intellectual disability (1); ischemia (1).